OGG1 (8-oxoguanine DNA glycosylase)
Diseases named in the same sentence as OGG1 in open-access papers (continued):
Sharing a sentence is not in itself a finding about the gene and the disease.
cancer (continued). "Importantly, data mining revealed that the mRNA level of SIRT2 was positively correlated with the OGG1 mRNA level in 18 of 33 different types of cancers, confirming that SIRT2 promotes OGG1 expression at the transcriptional level." (PMID 38554113, 2024). "The human glycosylase OGG1 extrudes and excises the oxidized DNA base 8-oxoguanine (8-oxoG) to initiate base excision repair and plays important roles in many pathological conditions such as cancer, inflammation, and neurodegenerative diseases." (PMID 39341999, 2024). "Notably, in this work, we analyzed 37 cancer-associated SIRT2 mutants, and only five of them exhibited loss of the stimulatory effect on OGG1 promoter activity and mRNA expression." (PMID 38554113, 2024). "Normally, 8-OHdG expression is regulated by hydrolysis or the cleavage of incorrectly bonded nucleotides by OGG1; impaired OGG1 activity damages DNA and cannot cleave guanosine, thus protecting the integrity of 8-OHdG, resulting in cancer development and a poor patient prognosis." (PMID 37760582, 2023). "The Impact of OGG1 on cancer development can thus be dissociated from its function in DNA repair." (PMID 38201575, 2023). "OGG1-enabled NFκB activity can promote cancer progression via a number of key mechanisms that include phenotypic transitions of cancer and stromal cells, expression and secretion of molecules that modulate innate immunity, and alteration of the vascular network." (PMID 38201575, 2023). "What is important for cancer is that OGG1 acts as a modulator of NFκB-driven gene expression." (PMID 38201575, 2023). "In addition to its effects on cancer and stromal cells, oxidative stress can modulate endothelial cell function, which is suggested by research on the OGG1-NFκB interaction in chromatin." (PMID 38201575, 2023). "Indeed, it was shown that several types of cultured cancer cells can be killed at micromolar concentrations of OGG1 inhibitors." (PMID 38201575, 2023). "We discuss here how this off-target effects may influence the interpretation of the results obtained upon exposure of the cells to OGG1 inhibitors and also which impact this could have for the therapeutical use of this molecules in cancer treatment." (PMID 36819096, 2023). "Interestingly, similarly to how OGG1 affects inflammatory gene expression, OGG1 also affects the expression of programmed death-ligand 1 (PD-L1) in cancer cells." (PMID 36497058, 2022). "Researchers speculate that the reduced OGG1 activity observed in fibrotic tissues and malignant cells may be a cellular defense against the extensive cytoskeletal changes required for cancer cell proliferation and migration." (PMID 35624797, 2022). "Long-term oxidative stress can lead to the continuous expression of OGG1-mediated inflammatory genes, leading to an excessive inflammatory response, which may lead to a series of diseases, such as cancer." (PMID 36620083, 2022). "Furthermore, OGG1 Ser326Cys seems to play a role in specific cancer types and a specific population." (PMID 36497058, 2022). "In humans, the OGG1 gene is localized on chromosome 3p25, a region frequently lost in cancer." (PMID 36178927, 2022). "OGG1 inhibition in cancer cells shows some promise as a new method of cancer treatment." (PMID 34227370, 2021). "The OGG1 enzyme of the BER pathway is less explored as an anti-cancer target." (PMID 34948899, 2021). "Lastly, OGG1 inhibition could provide therapeutic benefits by inhibiting the proliferation of cancers with high oxidative stress and sensitizing tumor cells to apoptosis with chemotherapy and radiotherapy." (PMID 33203705, 2021). "More specifically, OGG1 Cys326 has been related to an increased cancer risk in the rectum but not at other sites in the colon." (PMID 34199885, 2021). "Therefore, studying the effect of oxidation on the function of OGG1 is important for understanding molecular mechanisms of cancer and defining the correlation between oxidative stress and cancer." (PMID 33203705, 2021).
cancer (continued). "All these observations may provide new therapeutic windows in cancer therapy that might be exploited with selective drugs that specifically target Ogg1 and Neil1." (PMID 32192183, 2020). "Our results allow speculating TDP1 inhibition as a factor to increase OGG1-mediated DNA damage in cancer cells which lost redox homeostasis resulting in oxidative DNA damage." (PMID 33505969, 2020). "In line with this hypothesis, we show that OGG1 inhibitors (OGG1i) target a wide range of cancer cells, with a favourable therapeutic index compared to non-transformed cells." (PMID 33211885, 2020). "Here we hypothesize that OGG1 may represent an attractive target to exploit reactive oxygen species (ROS) elevation in cancer." (PMID 33211885, 2020). "The potential for OGG1 inhibitors for use as a monotherapy in cancer treatment has been shown by the increased sensitivity of cells from patients with MMR deficiency that accumulate high levels of 8-oxoG, identifying a synthetic lethal relationship between MMR and BER." (PMID 32648895, 2020). "The high load of ROS in cancer cells and the relative abundance of guanines in GC-rich promoters and telomeres have prompted us and others to develop the first small-molecule OGG1 inhibitors." (PMID 33114607, 2020). "Genetic variants of hOGG1 may affect the expression and function of the OGG1 protein, thus contributing to the risk of cancer." (PMID 30429230, 2019). "When NDUFA4L2 was silenced, we observed a significant accumulation of 8-oxodG, as a consequence of a reactivation of oxidative phosphorylation and ROS production, and a reactive increased expression of the DNA repair enzyme OGG1, that prevents excessive oxidative DNA damage in cancer cells." (PMID 30538212, 2018). "Importantly, although 8-oxoG accumulates, CHD4 fails to bind with tumor suppressor gene promoter in OGG1-deleted cells, indicating the prior role of OGG1 over 8-oxoG in facilitating the evolution of cancer epigenetic abnormalities." (PMID 30043138, 2018). "Could the stimulation of OGG1 by CUT domains contribute to the increased resistance of cancer cells to radiation?" (PMID 28147323, 2017). "OGG1 knockdown by three distinct siRNA sensitized DLD-1 cancer cells to radiation." (PMID 28147323, 2017). "Thus, both from a gene knockdown approach and a chemical inhibition approach, OGG1 contributes to the resistance of cancer cells to radiation." (PMID 28147323, 2017). "This OGG1-MUTYH interaction demonstrates the possibility that two genes within the same pathway can be mutually influential in altering cancer susceptibility, although their gene products do not necessarily physically interact with each other." (PMID 27588484, 2016). "In this study we have shown how this variant can contribute to increase cancer risk in BRCA1 carriers, by reducing the mRNA OGG1 expression levels, increasing the DNA damage as a consequence of genomic instability generated, and shortening the telomeres in a synergic way with the BRCA1 mutation." (PMID 27015555, 2016). "However, the analysis of genetic variations in papillary neoplasms of low malignant potential (PNLMP) as compared with high grade or poorly differentiated cancer revealed some peculiarities concerning ERCC6 Met1097Val and OGG1 Ser326Cys polymorphisms." (PMID 26649138, 2016). "However, observation over a longer time period revealed the spontaneous development of lung adenoma/carcinoma in 18-month-old Ogg1-KO mice." (PMID 25029543, 2014). "Furthermore, combined deficiency of OGG1 and MYH glycosylases results in age-related accumulation of 8-oxoG in the DNA of the lungs and small intestine, with cumulative damage in the liver, ultimately increasing cancer susceptibility in Myh−/−/Ogg1−/− mice." (PMID 40813502, 2025). "Moreover, OGG1 depletion impairs cancer cell proliferation by inducing S-phase DNA damage, replication stress, and subsequent cell cycle arrest or apoptosis, thereby supporting OGG1 as a potential therapeutic target in cancer." (PMID 40813502, 2025).
cancer (continued). "Growing evidence suggests that inhibiting OGG1 may be useful in the treatment of certain cancers." (PMID 39851540, 2025). "Thus, OGG1 inhibitors are being developed as anti-cancer and anti-inflammatory agents." (PMID 39341999, 2024). "However, OGG1 and/or MUTYH-deficient HAP1 cancer cells may have developed strategies to adjust to increased oxidative stress and maintain resistance to apoptosis which has recently been demonstrated for NEIL DNA glycosylases." (PMID 39662289, 2024). "Interestingly, the same authors have recently proposed OGG1 as an anti-cancer target, given that TH5487 has been shown to arrest cell proliferation and induce replication stress, and OGG1 inhibitors (OGG1i) are now considered as potential effective anti-cancer treatments." (PMID 35619904, 2022). "Thus, OGG1 is a promising target for cancer diagnosis and treatment." (PMID 33203705, 2021). "Genetic variations, i.e. polymorphism of DNA repair enzymes and cofactors, 8-oxoguanine DNA glycosylase (OGG1), APE1, X-ray repair cross-complementing protein 1 (XRCC1), XPC, MSH3, RPA-CDK7 among others have been reported to be associated with cancer and neurodegenerative diseases." (PMID 28475635, 2017). "Moreover, in line with previous findings, inhibited or reduced DNA repair and enzymatic activities of OGG1 protein may potentially sensitize the tumour cells to therapeutic agents, making OGG1 an attractive molecular target in the treatment of cancer." (PMID 26089588, 2015). "Variants in the OGG1 gene might alter protein structure or function or create alternatively spliced proteins which may influence BER efficiency and hence affect individual susceptibility to cancers." (PMID 24893568, 2014). "RESULTS: We identified the DNA base lesion repair proteins OGG1 and APE1 as key mediators of transcriptional reprogramming that promote cancer cell plasticity and resistance to EGFR-TKIs." (PMID 41975505, 2026). "To delve deeper into the impact of OGG1/SYT7 axis on cancer metastasis in vivo, we first employed a zebrafish xenograft model, which allows quick analyses of cancer progression." (PMID 39235072, 2024). "Another OGG1 inhibitor, SU0268, has been shown to increase genomic 8-oxodG levels in cancer cells, while it had moderate cytotoxicity and good permeability in normal cells." (PMID 36768357, 2023). "Very promising observations were made with the OGG1 competitive inhibitors TH5487 and SU0268 that have been proposed to be potential new tools for cancer therapy and for the treatment of inflammatory diseases." (PMID 36819096, 2023). "Moreover, the repair of 8-oxoG by OGG1-BER is an important event in cancer therapy strategies based on a ROS-mediated mechanism, so the use of a ROS-inducing agent, in combination with 8-oxoG repair enzyme inhibitors, may be an attractive new approach to improving therapeutic outcomes." (PMID 36497058, 2022). "While acute telomeric 8-oxoG formation did not cause telomere dysfunction in cancer cells, repeated lesion production over a month decreased cell growth, and caused telomere shortening and losses, chromosome fusions and genomic instability, all of which were greatly exacerbated by OGG1 deficiency." (PMID 34869348, 2021). "For the OGG1 rs1052133, previous studies have shown that homozygous carriers of the variant appear to have reduced repair capacity toward oxidized DNA lesions, and previous evidence indicated higher levels of 8-oxoG in lung tissue of LC patients than in lung tissue of patients without cancer." (PMID 32257438, 2020). "This study adds OGG1 to the list of BER factors, e.g. PARP1, as potential targets for cancer treatment." (PMID 33211885, 2020). "In conclusion, we validate OGG1 as one more to the list of existing BER factors, e.g., PARP1, as potential targets for treatment of cancer." (PMID 33211885, 2020).
cancer (continued). "8-Oxoguanine DNA glycosylase 1 (OGG1) is an important protein in base excision repair (BER) pathway which plays a key role in maintaining genome integrity and preventing cancer development." (PMID 26089588, 2015). "Regarding the anatomical location of APE1, OGG1 and PARP-1, a decrease in gene expression was observed among patients with cancer in the rectum." (PMID 25268610, 2014). "Regarding the anatomical location, for APE1, OGG1 and PARP-1, there was a decrease in gene expression among the patients with cancer in the rectum compared with the colon." (PMID 25268610, 2014). "The OGG1 competitive inhibitors TH5487 and SU0268 were shown to have great promise and are considered potential novel strategies for the treatment of inflammatory illnesses and cancer therapy." (PMID 39851540, 2025). "It is intriguing that the chronic, but not the acute, formation of telomeric 8-oxoG in human cancer cells lacking OGG1, the enzyme that removes 8-oxoG, triggers DNA replication stress at telomeres and increases telomere loss." (PMID 38171574, 2024). "However, even with increased OGG1 activity, the repair of all of the DNA damage may not be completely achieved, leading to persistent genomic instability, which could increase the risk of cancer progression and metastasis." (PMID 36982562, 2023). "Some researchers found that Ogg1-/-mice shows significant 8-oxoG accumulation; however, it does not lead to cancer or affect life span and embryo development." (PMID 35624797, 2022). "Therefore, OGG1 inhibitors can be considered as a new tool to block BER and to induce oxidative DNA damage at telomeres inducing cancer cell death, alone or in combination with other drugs like methotrexate." (PMID 33568707, 2021). "As TH5487 selectively induces proliferation arrest in cancer cell lines but not in non-transformed cells, OGG1 serves as a potential target for cancer treatment." (PMID 33114607, 2020). "Importantly, OGG1 knockdown or inhibition, like CUX1 knockdown, sensitized DLD-1 cancer cells to radiation." (PMID 28147323, 2017). "Data pertaining to the habit of smoking was available only for a few of the included studies and the genotypes of OGG1 Ser326Cys stratified on the basis of smoking habit was also available only for cancer cases and not for the controls." (PMID 27026921, 2016). "OGG1 knockdown, dicoumarol-treatment or NQO1- cancer cells were spared." (PMID 26602448, 2015). "Two groups reported that Ogg1-KO mice are not cancer-prone within 50 weeks after birth even though increased accumulation of 8-oxo-dG in their genomic DNA was observed." (PMID 25029543, 2014). "It is noteworthy that 8.6% of the Mutyh/Ogg1-DKO mice also exhibited adenomas/carcinomas in their gastrointestinal tracts, which were never observed in wild-type mice." (PMID 25029543, 2014). "In the histological type subgroup analysis, the OGG1 Ser326Cys allele was significantly associated with risk of ADC, but not with cancers of the SCC, SCLC and LCC." (PMID 22540013, 2012). "Beside its mutational and genome instability potential, an increasing body of evidence has pointed at 8-oxoG as an epigenetic marker through which OGG1, with or without its catalytic activity, can either activate or repress the transcription of different cancer relevant genes." (PMID 36819096, 2023). "Two anti-cancer compounds ([O-]C1=C(CC2=CC=CC=C2)SC(=[N+]1CC(=O)NC3=NC=C(CC4=CC=CC=C4)S3)S and CCCN(CCC)[S]-(=O)(=O)C1=CC=C(C=C1)C(=O)NNC2=NC3=CC=C(Br)C=C3C(=N2)C4=CC=CC=C4) from Selleckchem.com were identified to occupy the active pocket of OGG1 and bind with greater affinity than Control TH5487." (PMID 34948899, 2021). "For example, mice lacking both OGG1 and MYH or NEIL1 and NTHL1 show strong cancer susceptibility." (PMID 28665322, 2017). "The human 8-oxoguanine DNA glycosylase OGG1 is involved in base excision repair (BER), one of several DNA repair mechanisms that may counteract the effects of chemo- and radiation therapy for the treatment of cancer." (PMID 26364627, 2015).
cancer (continued). "Suppression of MTH1 may be an efficient strategy for killing cancer cells; however, because MTH1 and OGG1 protect normal tissues from oxidative-stress-induced cell death, it is important that MTH1 inhibition does not increase the risk of healthy tissue degeneration." (PMID 25029543, 2014). "However, Mth1/Ogg1/Mutyh-triple KO mice spontaneously develop multiple cancers in various tissues, a phenomenon not observed in Mth1/Ogg1-double KO mice, which suggests that tumor susceptibility may be attributed to MUTYH." (PMID 39741341, 2025). "Furthermore, reduced activity of BER system involving MTH1, OGG1 and FEN1 in hypoxic conditions could lead to increased formation of observed oxidative DNA damage due to decreased repair capacity and thereby could render cancer cells less dependent to MTH1." (PMID 34831264, 2021). "Synergistic cytotoxicity was seen in cancer but not noncancerous cells and was reduced by the ROS inhibitor NAC or knockdown of OGG1, demonstrating that the cytotoxicity resulted from the repair of ATL-induced oxidative DNA damage." (PMID 32029902, 2020). "The mouse mutants individually lacking OGG1, NTHL1, NEIL1, NEIL2, or MYH or cells derived from these mutants are viable and do not develop a strong phenotype, such as accelerated aging or enhanced incidence of spontaneous cancer." (PMID 28665322, 2017).